GATD3 (glutamine amidotransferase class 1 domain containing 3)
Description:
Acts as a mitochondrial deglycase involved in the removal of early non-enzymatic glycation adducts from amino acids and nucleotides, thereby restricting the formation of advanced glycation end products (AGEs) within mitochondria. Required to maintain low levels of glycation on mitochondrial ribosomal RNA and proteins, supporting efficient mitochondrial gene expression. Contributes to mitochondrial homeostasis, normal respiratory capacity, and proper mitochondrial network organization. Acts also as a mitochondrial regulator of malate dehydrogenase MDH2 by competitively limiting the association of MDH2 with the mitochondrial deacetylase SIRT3, thereby preserving MDH2 acetylation and enzymatic activity. Through this mechanism, supports efficient conversion of malate to oxaloacetate, sustaining TCA cycle continuity and oxidative phosphorylation.
Synonyms: C21orf33; GATD3A; KNP-Ia; GT335; ES1; HES1; D21S2048E; KNPI; KNPH; KNP-I; GATD3B
Tractability: PROTAC: ubiquitination databases record sites on it.
Gene: Protein-coding gene on chromosome 21 (44,133,610 to 44,210,114, forward strand). Ensembl gene ENSG00000160221.
Subcellular location: Mitochondrion matrix
Subcellular location (Human Protein Atlas): Mitochondria; Centrosome
Gene Ontology:
Molecular function: protein binding
Cellular component: mitochondrion; mitochondrial matrix
Homologues: Orthologues: chimpanzee GATD3 (99% identical), mouse Gatd3a (90% identical), rat Gatd3a (88% identical), guinea pig GATD3 (87% identical), dog GATD3 (83% identical), zebrafish gatd3 (74% identical), macaque GATD3 (68% identical), pig GATD3 (61% identical).
Diseases named in the same sentence as GATD3 in open-access papers:
GATD3 is named in the same sentence as 16 diseases in open-access papers, as found by Europe PMC text mining. Sharing a sentence is not in itself a finding about the gene and the disease.
GATD3 shares sentences with these, for which no sentence is quoted: Achalasia (1 paper); Alzheimer disease (1); asthenospermia (1); Ataxia (1); cancer (1); cone dystrophies (1); congenital heart disease (1); dementia (1); dilated cardiomyopathy (1); Down syndrome (1); leukemia (1); neurological diseases (1); osteoarthritis (1); pancreatic cancer (1); Parkinson’s (1); schizophrenia (1).